INS (insulin)
Diseases named in the same sentence as INS in open-access papers (continued):
Sharing a sentence is not in itself a finding about the gene and the disease.
Insulin resistance (continued). "Insulin resistance, which might be present in T1D women due to glucotoxicity, abnormal fat mass distribution, and excess weight, may also contribute to worsen exogenous hyperinsulinism by increasing insulin requirements." (PMID 40747135, 2025). "However, chronic insulin administration may further reduce hepatic insulin clearance, and promote adipogenesis, creating a vicious cycle of weight gain and worsening insulin resistance (OR: 1.4 per 5‐year age increase; 95% CI: 1.1–1.8)." (PMID 41383356, 2025). "Moreover, insulin resistance may directly blunt GH-induced intracellular signaling, as insulin has been shown to downregulate GH receptor (GHR) expression and impair JAK2/STAT5 activation—key pathways for GH-mediated growth promotion." (PMID 41282298, 2025). "Additionally, we examined whether NPT levels correlate with other hormonal factors—such as insulin, leptin, or ghrelin —which play key roles in the pathogenesis of insulin resistance." (PMID 41007299, 2025). "Moreover, the resultant insulin resistance might perpetuate hyperinsulinemia by inducing even greater insulin secretion to accommodate for hyperglycemia." (PMID 40013621, 2025). "However, when insulin function is impaired, it results in a pathological state known as “insulin resistance” (IR), characterized by reduced insulin-mediated glucose control, diminished glucose utilization, abnormal lipid accumulation, and heightened lipid degradation in adipocytes." (PMID 40857248, 2025). "Given insulin resistance has been associated with impaired postprandial satiety signalling and incretin responses (particularly GLP-1), short-term improvements in insulin sensitivity could contribute to the potentially subtle augmented exercise-related total GLP-1 responses in South Asians." (PMID 40425789, 2025). "Furthermore, the study did not explore the relationships between TyG and TyG/HDL-c with other metabolic syndrome-related indicators (such as insulin and homeostasis model assessment of insulin resistance [HOMA-IR]), which presents an opportunity for future research." (PMID 40626240, 2025). "Directly evaluating mitochondrial function by measuring ATP levels in muscle tissue and quantifying blood insulin and glucose levels to evaluate insulin resistance may help to elucidate the mechanisms of the anti-obesity effect of heat-killed F. fructosus OS-1010." (PMID 40783584, 2025). "Pollutant (e.g., VOCs) exposure can lead to oxidative stress and inflammatory responses and might result in impaired insulin signaling in insulin-sensitive target tissues (including muscle, liver, and adipose tissue), which can in turn trigger insulin resistance." (PMID 39853044, 2025). "Similarly, progressive resistance training improved not only muscle strength but also waist circumference, fasting glucose, basal insulin levels, and insulin resistance in older women, with additional reductions in glucose and waist circumference observed in women with metabolic syndrome." (PMID 41357171, 2025). "Moreover, SO2-induced endothelial dysfunction, characterized by reduced NO bioavailability and vascular inflammation, may impair insulin signaling and contribute to insulin resistance." (PMID 41009549, 2025). "Additionally, this study highlighted a correlation between FGF-21 levels and insulin resistance indicators, such as fasting insulin, measurements from the first and second hours of the oral glucose tolerance test (OGTT), and the HOMA index, as well as triglycerides, HDL, VLDL, uric acid, and GGT." (PMID 40559404, 2025). "Thus, cortisol and aldosterone levels are associated with insulin secretion and/or insulin resistance in individuals without type 2 diabetes." (PMID 40296149, 2025). "Increased blood glucose and insulin levels, along with signs of insulin resistance and glucose intolerance, were consistent across all three generations indicating a transgenerational inheritance of metabolic dysfunction, particularly within insulin signaling pathways." (PMID 40606827, 2025).
Insulin resistance (continued). "Notably, n3 PUFAs play a crucial role due to their anti-inflammatory properties and their ability to regulate glucose metabolism, lipid profiles, and insulin sensitivity, making them particularly beneficial for conditions such as metabolic syndrome or insulin resistance." (PMID 40278260, 2025). "Notably, IRF5 expression in overweight/obese males, but not females, was significantly associated with metabolic dysfunction, showing positive correlations with fasting blood glucose, HbA1c, insulin, and homeostatic model assessment for insulin resistance (HOMA-IR) levels." (PMID 40943154, 2025). "Furthermore, individuals with both insulin deficiency and insulin resistance were at a higher risk for developing T2D and required insulin treatment earlier than those without." (PMID 40490745, 2025). "Elevated insulin levels in young MHS subjects may help regulate FBS within a healthy range, counteracting calcium‐linked irregularities in glucose and glycogen metabolism and help mitigate developing insulin resistance in skeletal muscle." (PMID 40329491, 2025). "Consequently, insulin secretion becomes impaired, leading to the onset of insulin resistance." (PMID 41462642, 2025). "Moreover, they may interfere with insulin signaling pathways, further worsening insulin resistance and lipid metabolism disorders in these obese rats." (PMID 40298780, 2025). "Together, these adipokines provide a broader framework for understanding the underlying mechanisms of insulin resistance and could complement traditional diagnostic tools, such as the HOMA-IR index, fasting glucose and insulin measurements, or insulin resistance risk scales." (PMID 40289929, 2025). "Given that some cases of T2D primarily involve impaired insulin secretion rather than insulin resistance, we further explored the association between the TyG index and mortality in individuals not on insulin therapy who had fasting insulin levels below the median." (PMID 40065340, 2025). "Furthermore, the recognized roles of chronic inflammation and insulin resistance in PV suggest that cytoreductive therapy may indirectly improve glucose metabolism by reducing the inflammatory burden and cytokine-driven insulin signaling disruptions." (PMID 41003014, 2025). "There is also an insulin sensitivity index (Si), which may suggest severe insulin resistance." (PMID 40565151, 2025). "Mechanisms including altered adipokine secretion, impaired insulin secretion upon metabolic stimuli and earlier onset of adipocyte maturation arrest as well as ‘premature insulin resistance’ during weight gain could be factors increasing the cardiometabolic risk of Asian populations at a lower BMI." (PMID 40069923, 2025). "Similarly, APOH has been found to induce ER stress during hepatitis B infection, APOB100 is associated with lipid-induced ER stress and hepatic insulin resistance, and APOCIII has been shown to cause ER stress and inflammation, while also impairing insulin signaling in mouse skeletal muscle cells." (PMID 41366770, 2025). "Therefore, when combined, metformin and CBD should exert a considerable beneficial synergistic metabolic effect, improving insulin signaling, reducing oxidative stress, and enhancing mitochondrial function, thereby offering a novel therapeutic avenue for insulin resistance." (PMID 40243433, 2025). "Furthermore, SGC effectively increased insulin sensitivity and mitigated insulin resistance." (PMID 41149577, 2025). "This inverse relationship might stem from lead's interference with glucose metabolism and insulin signaling pathways, which could prompt insulin resistance, and its effects on lipid metabolism, potentially impacting liver functions and serum triglyceride concentrations." (PMID 39948676, 2025). "Dysfunctional ERAD may lead to insulin resistance in insulin target tissues." (PMID 41465472, 2025).
Insulin resistance (continued). "Similarly, the relationship between “insulin resistance” and “adipose tissue macrophages (ATMs)” has been extensively studied, with evidence indicating that macrophage-derived exosomes play a key role in regulating insulin sensitivity." (PMID 40453651, 2025). "The findings indicated that PSP treatment in T2DM mice could obviously decrease the fasting blood glucose and fasting insulin levels, ameliorate glucose tolerance, insulin resistance, lipid, and inflammatory factor levels, attenuate pancreatic and liver damage, and increase the fecal SCFA content." (PMID 40278571, 2025). "When hyperinsulinemia is a compensatory response to insulin resistance as proposed in the traditional view, an increase in plasma insulin concentrations and insulin therapy may overcome insulin resistance and help to achieve a better metabolic control and long-term outcome." (PMID 41009753, 2025). "For instance, the suppression of insulin production during torpor mimics certain aspects of insulin resistance, while the protective roles of miRNAs like miR-125a-5p could inform therapeutic strategies for mitigating oxidative stress in chronic metabolic diseases." (PMID 40427509, 2025). "The complex interplay between mitochondrial integrity and insulin sensitivity has attracted considerable scrutiny in contemporary research, demonstrating that compromised mitochondrial functionality can initiate a series of metabolic disruptions leading to insulin resistance." (PMID 40862129, 2025). "Our data corroborated the assumption that physical exercise, even without great weight loss, is capable of improving beta cell function and glucose/insulin homeostasis, and could be beneficial as a complementary treatment to prevent insulin resistance or T2D progression." (PMID 40561274, 2025). "This bidirectional relationship highlights the complexity of metabolic disorder development, where hyperinsulinemia may initiate or exacerbate insulin resistance, particularly when insulin receptors are dysfunctional or when the secreted insulin exhibits reduced biological activity." (PMID 40868096, 2025). "This could be attributed to either higher expression of cathepsin enzymes or the increased acidic nature of the lysosomes, which favors more rapid dissociation of insulin from the insulin receptor in LL:AA myotubes, thereby terminating insulin signaling and contributing to insulin resistance." (PMID 41004571, 2025). "The tendency we observed for increased β-hCG at the beginning of pregnancy in the GDM subgroup that later received insulin might reflect more severe insulin resistance - and thus less impact on the trophoblast - compared to the subgroup that underwent dietary intervention." (PMID 40970032, 2025). "In participants without past COVID-19 status, fasting plasma glucose, insulin and total cholesterol could significantly associate with insulin resistance measured by HOMA-IR." (PMID 40273152, 2025). "This work found that early‐stage insulin sensitization but late‐stage insulin resistance in prenatal caffeine exposure (PCE)‐ induced intrauterine growth restriction (IUGR) offspring may be related to the hepatic AGEs accumulation via intrauterine GR/miR‐1224 programming by glucocorticoids." (PMID 40903796, 2025). "In addition, glucose tolerance and insulin tolerance tests after 35 days of patch-controlled hNORM treatment confirmed the reversal of chronic insulin resistance as well as hyperglycaemia, and the treated animals showed normal postprandial glucose-control and insulin-response dynamics." (PMID 39953326, 2025). "However, elevated levels of circulating BCAA may be a sign of increasing insulin resistance and the result of reduced insulin action." (PMID 39791169, 2025). "Indeed, elevated insulin levels and insulin resistance prior to DM onset may be due to a decline in hepatic insulin clearance." (PMID 40924301, 2025).
Insulin resistance (continued). "Furthermore, FAUST analysis showed that, under basal conditions, there was a different distribution of the eight platelet subpopulations comparing advanced insulin resistance and normal insulin sensitivity groups, with differences also detected following PGI2 inhibition." (PMID 40304758, 2025). "Finally, insulin’s anti-lipolytic function is dysregulated in cases of insulin resistance, which may facilitate hepatic TG synthesis." (PMID 39941760, 2025). "Data from large-scale cohort such as MASHAD study in Iran and the Finnish GOAL cohort, showed that hyperuricemia is independently associated with higher fasting glucose, insulin and surrogate indices of insulin resistance such as HOMA-IR and TyG even in non-diabetic populations." (PMID 40943711, 2025). "Therefore, insulin resistance can be treated on the one hand by lifestyle changes, with physical activity and diet being important in this case; on the other hand, drug treatment can improve insulin response, thus reducing insulin demand." (PMID 41020831, 2025). "Moreover, insulin resistance is a hallmark of metabolic syndrome, cancer, and CKM-related complications; dysregulation of insulin signaling contributes to diabetic cardiomyopathy, atherosclerosis, and hyperinsulinemia-driven tumorigenesis, particularly in colorectal and breast cancers." (PMID 40227756, 2025). "Dysglycemia is almost universal in the first weeks after transplantation: insulin resistance is promoted by postsurgical inflammation, and high-dose immunosuppressive medications promote insulin resistance; in addition, patients receiving tacrolimus present an impaired insulin production." (PMID 40566549, 2025). "Diabetic animals exhibited characteristic T2DM features including moderate hyperglycemia (245.8 ± 28.6 vs. 98.6 ± 8.3 mg/dL in controls), elevated HOMA-IR values (3.8 ± 0.7), and preserved but elevated insulin levels, confirming insulin resistance rather than absolute insulin deficiency." (PMID 40723442, 2025). "Because the MAPK pathway is largely concerned with growth, proliferation, and differentiation of the cell, rather than any of the metabolic functions associated with insulin, this would concern what is endorsing the preferential activation of this pathway in insulin resistance." (PMID 40989682, 2025). "Moreover, this dietary intervention may enhance insulin sensitivity and diminish insulin resistance, facilitating more efficient insulin utilization and promoting glucose uptake into cells." (PMID 41458553, 2025). "Additionally, it may regulate blood glucose levels by influencing insulin secretion and insulin resistance, contributing to long-term beneficial effects on overall metabolism." (PMID 41217190, 2025). "Consequently, this may be interpreted as a settling period, as the temporary insulin resistance is a precursor to the development of sustained improvements in insulin sensitivity." (PMID 40005307, 2025). "Decreased insulin sensitivity has been associated with elevated levels of IGFBPs, prompting the hypothesis that changes in IGFBP expression may be biomarkers of maternal insulin resistance during pregnancy." (PMID 41333061, 2025). "However, when hyperinsulinemia is the primary defect that triggers insulin resistance, as proposed in the alternative model, therapeutic strategies should primarily focus on reducing plasma insulin concentrations to improve metabolic control and long-term outcomes." (PMID 41009753, 2025). "Thus, strategies aimed to break the perpetuating cycle of weight gain, insulin resistance and increased exogenous insulin requirements are highly desirable in patients with double diabetes, where clinical features of both T1D and T2D coexist in the same subject." (PMID 40004833, 2025). "Thus, insulin resistance in the liver in T2D did not simply involve a loss of canonical insulin signaling but the also appearance of new phosphorylations representing a change in the balance of multiple kinases." (PMID 40231468, 2025).
Insulin resistance (continued). "With equivalent baseline levels of insulin sensitivity in the 2 groups, the results of the intervention would more directly reflect the isolated effect of energy restriction without the confounding effect of different levels of peripheral insulin resistance influencing the results." (PMID 40309768, 2025). "It is suggested that pregnant women with GDM may not produce enough insulin to overcome the increased insulin resistance caused by hormonal changes during pregnancy." (PMID 38274586, 2024). "Thus, according to Bergman’s hypothesis, reduced hepatic insulin clearance is the primary event that leads to the subsequent development of (peripheral) hyperinsulinemia and insulin resistance." (PMID 39769002, 2024). "Moreover, while we have shown that the irisin/AMPK pathway can decrease insulin resistance and improve insulin sensitivity during exercise, its specific impacts on insulin resistance pathways remain unclear." (PMID 38724553, 2024). "We may thus speculate that, under conditions of insulin resistance or low insulin levels, other immune cells such as lymphocytes, monocytes/macrophages and neutrophils may become suppressed as a consequence of their partial dependence on GLUT4 for glucose uptake." (PMID 38565760, 2024). "Furthermore, fructose may induce insulin resistance, impair glucose tolerance, and elevate circulating insulin levels, thereby indirectly increasing serum uric acid levels." (PMID 38999914, 2024). "Insulin resistance, which plays a pivotal role in the pathophysiology of T2D, hypertension, dyslipidemia and MetS, is characterized by reduced sensitivity of tissues to insulin, which is evident from the higher insulin concentrations necessary to reach optimal effect." (PMID 39064282, 2024). "In addition, we observed glucose intolerance, fasting glucose increased and damage to the insulin signaling pathway, which may indicate insulin resistance." (PMID 38660995, 2024). "Moreover, IMD can reduce the levels of fasting blood glucose (FBG), insulin, free fatty acid, triglycerides, and total cholesterol, thereby improving metabolic syndromes like obesity and insulin resistance in T1DM rats, T2DM mice, hyperhomocysteinemia mice, and ApoE−/− atherosclerosis mice." (PMID 39338366, 2024). "Both studies found that metabolic syndrome and insulin resistance were significantly higher in patients with androgenic alopecia, with specifically elevated body mass index, blood pressure, fasting glucose, high-density lipoprotein, and fasting insulin among patients with alopecia." (PMID 39135763, 2024). "However, patients with T2D may develop insulin resistance, which may compromise the physiological effects of insulin on bones." (PMID 38654244, 2024). "These evidences suggest that AC could improve a variety of symptoms in patients with OPCOS, as evidenced by lowering LH/FSH, increasing follicle diameter and endometrial thickness, lowering T levels, improving insulin resistance, as well as improving fasting blood glucose and fasting insulin levels." (PMID 39749020, 2024). "Furthermore, studies have revealed that ASs may affect blood sugar levels and result in insulin resistance either via impairing the normal cephalic response to food, or through the modulation of insulin and incretin production." (PMID 39339762, 2024). "Moreover, PGA-K reduced the levels of insulin resistance markers, including insulin and leptin." (PMID 38542720, 2024). "Furthermore, it has been shown that accumulation of ang2 could also reduce insulin secretion, lead to insulin resistance, and impair glucose metabolism." (PMID 38400070, 2024). "Therefore, the results may be due to ethnic differences as Asians tend to have lower insulin sensitivity and higher insulin resistance than Caucasians, according to relevant research." (PMID 39683407, 2024). "Initially, the pancreas may produce extra insulin to compensate for insulin resistance." (PMID 39114126, 2024).